GHR (growth hormone receptor)
Diseases named in the same sentence as GHR in open-access papers (continued):
Sharing a sentence is not in itself a finding about the gene and the disease.
breast carcinoma (continued). "In MDA-MB-231 and MCF7 human mammary carcinoma cells, GH induced chemoresistance to doxorubicin by suppressing apoptosis, and these effects were reversed by the GHR antagonist pegvisomant." (PMID 31939481, 2019). "GH transcription and protein expression was documented in human breast cancer and endometrial tissue and in hepatocellular carcinoma, while GHR is expressed in several human cancers." (PMID 31939481, 2019). "Experimental studies have shown that inhibition of GHR signaling leads to reduced breast cancer cell proliferation." (PMID 30617282, 2019). "In general, ER−ve breast cancers are highly invasive; thus, we examined the effect of GHR silencing on cell invasion and migration." (PMID 30617282, 2019). "Several different types of human cancers, including cancers of breast, colon, thyroid, blood, skin, pancreas, liver, endometrium, kidney, lung, stomach, glia, thymus, and brain express GHR." (PMID 32382711, 2019). "High GHR mRNA expression in ER−ve breast cancer patients (n = 671) was associated with a significantly poor survival probability (HR−1.26; p = 0.041) compared to ER−ve breast cancer patients with low expression of GHR." (PMID 30617282, 2019). "GHR silencing appeared to concomitantly increase drug-induced apoptosis, and reduced cell viability, migration and invasion properties of the breast cancer cells in vitro and in vivo." (PMID 32382711, 2019). "Together, these results suggest that GHR inhibition increases chemosensitivity of ER−ve breast cancer cells." (PMID 30617282, 2019). "Autocrine GH in GHR-expressing breast cancers have been shown to possess higher metastatic and invasive potential." (PMID 31547367, 2019). "Nevertheless, other hormone receptors such as prolactin receptor (PRLR) or growth hormone receptor (GHR) have been evaluated in human breast cancer." (PMID 27649560, 2016). "Herein, the ESR1, PGR, PRLR and GHR gene expression were analyzed and the results showed all hormone receptors to be significantly lower expressed in malignant mammary tumors compared to the group of reference tissue and benign tumors." (PMID 27649560, 2016). "In benign (p<0.0001) and malignant mammary tumors (p = 0.009) significant differences were observed in the gene expression of GHR with a higher expression in FFPE samples." (PMID 27649560, 2016). "In breast cancer, the GHR promotes progression via the MAPK pathway." (PMID 39459020, 2024). "In mammary tumor cells, GH and GHR may be co-expressed, resulting in the autocrine intracellular activation of the GH/GHR system, which is inaccessible for drugs that only compete for the GH/GHR interaction at the cell surface." (PMID 39459020, 2024). "Besides, it has been demonstrated that GH inhibits the JNK pathway through the activation of GHR in breast cancer cells." (PMID 33621201, 2021). "In addition, GHR inhibition induced significant decrease of breast cancer cell growth by 3‐(4,5‐dimethylthiazol‐2‐yl)‐2,5‐diphenyl‐tetrazolium bromide assay." (PMID 32069380, 2020). "In this case, the combined use of PRLR or GHR inhibitors may produce better anti-breast cancer potential than PRLR or GHR inhibitors alone." (PMID 33362552, 2020). "Furthermore, recent study from Frank’s team shows that there is a GHR-PRLR hybrid receptor on breast cancer." (PMID 33362552, 2020). "In addition, GHR is connected with breast cancer chemoresistance and metastasis that GHR knockdown decreases the chemoresistant and metastatic behavior of estrogen receptor negative breast cancer." (PMID 32970612, 2020). "Silencing GHR inhibited the activation of the BRAF/MEK/ERK signaling pathway, which might be one of the mechanisms underlying breast cancer progression inhibition caused by GH suppression." (PMID 32069380, 2020). "Our data indicate that GHR knockdown effectively suppresses the metastatic behavior of aggressive ER−ve breast cancer cells, clearly suggesting an important role for GHR in ER−ve breast cancer metastasis." (PMID 30617282, 2019).
breast carcinoma (continued). "GHR signaling is known to be involved in breast cancer development and progression." (PMID 30617282, 2019). "In light of these published data, we hypothesized that targeting GHR in highly aggressive ER−ve breast cancers would inhibit cancer progression and further sensitize the ER−ve breast cancer cells to chemotherapeutic drugs." (PMID 30617282, 2019). "Furthermore, 63% of ER−ve and 37% of ER+ve breast cancers had moderate to high levels of GHR expression." (PMID 30617282, 2019). "Furthermore, analysis of the colony-forming ability revealed that GHR silencing significantly reduced the number of colonies that formed in ER−ve breast cancer cell lines (95% reduction in MDA-MB-231 cells and 88% reduction in BT-20 cells)." (PMID 30617282, 2019). "In this report, we demonstrate that GHR is positively associated with ER−ve breast tumor progression, chemoresistance, and metastasis and find that GHR could serve as a potential therapeutic target for the treatment of aggressive breast cancers." (PMID 30617282, 2019). "Blockade of GHR using neutralizing antibody or pharmacological inhibition of JAK2/STAT5 inhibits ABCG2 promoter activity suggesting that GHR regulates ABCG2 through JAK2/STAT5 signaling mechanism in ER−ve breast cancers." (PMID 30617282, 2019). "Furthermore, to identify the expression of GHR during cancer progression, we evaluated GHR expression in normal mammary glands, preneoplastic mammary lesion, and tumor tissues collected from an ER−ve mouse mammary tumor model." (PMID 30617282, 2019). "Furthermore, the level of GHR is upregulated in breast cancer and lung cancer." (PMID 33562824, 2021). "This study indicates that H53 exhibits potential biological activity against breast tumors, which implies that internal image anti-idiotypic antibodies may be a useful strategy for the development of PRLR/GHR dual-function antagonists for breast cancer therapy." (PMID 33362552, 2020). "To test whether GH signaling in human T47D breast cancer cells, which express low levels of GHR and high levels of PrlR, is affected by extracellular acidosis, we assessed GH induction of phosphorylation of Jak2, Jak1 and Stat5 across a range of zinc ion concentrations at pHe 7.4 and 6.8." (PMID 24004716, 2013). "The growth hormone receptor (GHR) is overexpressed in many solid tumors and promotes tumor proliferation, progression, and metastasis in breast cancer via the BRAF/MEK/ERK pathway." (PMID 37245006, 2023). "The breast cancer cell line, MCF-7, which is known to express GHR and PRLR mRNA (Cancer Cell Line Encyclopedia) was used as a positive control." (PMID 37043098, 2023). "Multiple studies suggest that PRL and GH promotes breast cancer growth, leading to wide interest in PRLR/GHR as a potential target for breast cancer therapy." (PMID 33362552, 2020). "GHR was recently reported to mediate cell progression and apoptosis via the BRAF/MEK/ERK signaling pathway in breast cancer." (PMID 33330065, 2020). "To evaluate the impact of GHR on ER−ve breast cancer aggressiveness, we used shRNAs to silence GHR expression in MDA-MB-231 and BT-20 cells, which express high levels of GHR." (PMID 30617282, 2019). "Further, protection of endocrine-resistant breast cancer from ruxolitinib, a JAK2-inhibitor, was reported to coincide with GHR expression." (PMID 32382711, 2019). "First to investigate the effect of GHR silencing or ABCG2 silencing on cancer progression, we used wild type or GHR knockdown or ABCG2 knockdown primary human breast cancer cells." (PMID 30617282, 2019). "Meanwhile, in the C3A human liver cancer cells, MCF-7 breast cancer cells and CFPAC-1 pancreatic cancer cells treated by MR-409, there was also a dramatic decrease in phosphorylation of GHR/JAK2/STAT5." (PMID 29983893, 2018). "Gene expression of ERα (ESR1), PGR, PRLR, GHR and CDH-1 was detected in normal mammary tissues and in all mammary neoplasms, except in one carcinoma." (PMID 26370564, 2015).
breast carcinoma (continued). "Higher GHR, IGF-1, and IGF-1R expression are observed on breast cancer cells in humans." (PMID 34530525, 2021). "MDA‐MB‐231 breast cancer cells with or without GHR silencing were subcutaneously injected into the right flank region of female mice to establish xenograft mouse models." (PMID 32069380, 2020). "In addition, inhibition of GHR signaling sensitized breast cancer cells to chemotherapy by decreasing ABCG2, which resulted in lowering the drug effluxing capabilities of ER−ve breast cancer cells." (PMID 30617282, 2019). "Growth hormone receptor (GHR) plays a vital role in breast cancer chemoresistance and metastasis but the mechanism is not fully understood." (PMID 30617282, 2019). "The analysis showed that there was a significant increase in GHR expression in breast cancer tissues compared to adjacent normal tissues (p < 0.001)." (PMID 30617282, 2019). "Collectively, our data indicates that at physiological zinc ion levels GH-induced Stat5 activation via PrlR, but not GHR, in breast cancer cells is significantly suppressed by moderate extracellular acidosis." (PMID 24004716, 2013). "GH/GHR could mediate the TME and signal transduction including JAK/STAT, MAPK/phosphatidyl inositol 3 kinase (PI3K)/Akt, matrix metallopeptidase 2, and VEGF/VEHGR in gastric cancer, breast cancer, and melanoma." (PMID 36016614, 2022). "As PRLR and growth hormone receptor (GHR) are closely involved in the incidence and development of breast cancer which typically express PRLR, GHR, and GHR-PRLR heterodimers, the use of a combination PRLR and GHR antagonists may be a better strategy for breast cancer treatment." (PMID 36714582, 2022). "We determined if GHR could be a potential therapeutic target for estrogen receptor negative (ER−ve) breast cancer, which are highly chemoresistant and metastatic." (PMID 30617282, 2019). "For PRLR and GHR no detailed studies on histopathological subtypes or their possible prognostic value in canine mammary tissue have been carried out yet in contrast to human breast cancer." (PMID 27649560, 2016).
diabetes (28 papers, 2011 to 2025). "GHR was previously associated with fibromyalgia, chronic pain, diabetes, and age-related pathologies including inflammatory disorders, stroke, and neurodegenerative diseases." (PMID 39847262, 2025). "Association between GHR and NAFLD stratified by gender, age, race, diabetes, moderate activities and BMI." (PMID 39296907, 2024). "Hazard ratios (HR) of heterozygotes vs. homozygotes of GHR SNP rs4130113 and other models with total mortality in men with diabetes, hypertension, CHD and cancer." (PMID 34074802, 2021). "Global GHR−/− mice are exceptionally long-lived and have improved glucose homeostasis and resistance to diabetes and cancer." (PMID 26233957, 2015). "Notably, we observed decreased levels of branched chain amino acids (BCAAs, p = 0.0344) in GHR-KO pigs, which is of particular interest, as increased BCAA levels are considered as risk factor for the development of diabetes." (PMID 41125144, 2025). "Reduction in growth hormone (GH) signaling throughout life is known to extend lifespan and enhance healthspan in mice, and congenital GH receptor (GHR) mutations in both mice and humans confer protection against age-related diseases such as cancer, diabetes, and cognitive decline." (PMID 41350448, 2025). "The correlation between GHR and the risk of NAFLD was stronger among other race (OR = 1.42, p interaction =0.011), participants with age <50 years old (OR = 1.38, p interaction <0.001), and those with non-diabetes (OR = 1.36, p interaction <0.001)." (PMID 39296907, 2024). "Conversely, in another prospective study it was shown that mutations in the growth hormone receptor (GHR) gene lead to reduced IGF-1 levels, which are associated with severe short stature in the subjects concerned and significantly reduced diabetes and BC risks." (PMID 36085535, 2022). "Taken together, our study adds to the growing evidence that RYGB decreases GHR-dependent signaling in the liver, and supports that this reduction may contribute to lowering of glucose and robust improvements in diabetes control." (PMID 34845204, 2021). "In the present longitudinal study, we tested the hypothesis that genetic variation in GHR affects lifespan at least in part by protection against the detrimental effects of one or more aging-related diseases, namely diabetes, hypertension, coronary heart disease, and/or cancer." (PMID 34074802, 2021). "The findings suggest a notably stronger correlation between GHR and the prevalence of NAFLD among individuals under 50 years old and those with non-diabetes." (PMID 39296907, 2024). "Mice in which the genes for growth hormone (GH) or GH receptor (GHR−/−) are disrupted from conception are dwarfs, possess low levels of IGF‐1 and insulin, have low rates of cancer and diabetes, and are extremely long‐lived." (PMID 26268661, 2015). "For the kinase MAP3K5 it was hypertension, CHD and diabetes, for the kinase receptor PIK3R1 hypertension, CHD and stroke, and for the growth hormone receptor gene (GHR) and vascular endothelial growth factor receptor 1 gene (FLT1), it was nullifying the higher mortality risk posed by hypertension." (PMID 37561089, 2023). "No genetic effects of GHR genotype on mortality were apparent in subjects with diabetes, CHD and cancer after Bonferroni correction." (PMID 34074802, 2021). "It was also shown that a population carrying mutations in the growth hormone receptor gene has lower expression levels of the growth hormone receptor and IGF-I, while exhibiting a very low incidence of cancer and absence of diabetes." (PMID 23497114, 2013). "The three studies used for the diabetes comparison represent the largest candidate protein characterisations of type 2 diabetes to date and the top markers identified included aminoacylase-1 (ACY-1), sex hormone-binding globulin (SHBG) and growth hormone receptor (GHR)." (PMID 35023833, 2022).
diabetes (continued). "Such divergent behaviour of GHR and IGF‐1 receptor mRNA in HF has been described in other pathological conditions, including diabetes and malnutrition, in which the two mRNAs are not coordinately regulated in all tissues studied." (PMID 33512777, 2021).
melanoma (21 papers, 2016 to 2025). A malignant, usually aggressive tumor composed of atypical, neoplastic melanocytes. "Furthermore increased lung nodule formation in DJ-1 KO mice is inhibited by intravenous injection of GHR-deficient melanoma cells." (PMID 27825319, 2016). "In conclusion, our study provides a first pre-clinical validation of the hypothesis that targeting GHR can improve anti-cancer therapeutic success in vivo for two different human cancers associated with marked drug resistance and high lethality – melanoma and hepatocellular carcinoma." (PMID 35865483, 2022). "Furthermore, we found that treatment with GH increases lung nodule formation, following intravenous injection of melanoma cells in wild-type mice and increased lung nodule formation in DJ-1 KO mice can be inhibited by intravenous injection of GHR-deficient melanoma cells." (PMID 27825319, 2016). "Consistent with our earlier findings, GHR inhibition has previously been shown to sensitize melanoma cells to paclitaxel, cisplatin, and the pyrimidine analog fluorouracil (5-FU)." (PMID 41515995, 2025). "Activation of this downstream pathway by refolded mGH was assessed in a mouse melanoma cell line, B16-F10, which expressed the GHR." (PMID 40549028, 2025). "In our previous study, we observed elevated levels of GH and GHR RNA in SK-MEL-28 melanoma cells following treatment with chemotherapies, including doxorubicin." (PMID 39123364, 2024). "We treated the melanoma cells with GH, doxorubicin, and the GHR antagonist, pegvisomant, and analyzed the exosomes released." (PMID 39123364, 2024). "We have previously shown that GHR inhibition sensitizes melanoma cells to paclitaxel, as well as platinum-based antineoplastic drugs like cisplatin and the pyrimidine analog, fluorouracil (5-FU)." (PMID 39000545, 2024). "We and others have recently shown that in cancers of the liver, breast, endometrium, and melanoma, GHR attenuation markedly improves chemotherapeutic efficacy in preclinical models." (PMID 39000545, 2024). "This understanding provides insights into the mechanisms of GH in melanoma chemoresistance and suggests GHR antagonism as a potential therapy to overcome chemoresistance in melanoma treatment." (PMID 39123364, 2024). "Our group has previously shown that GH increases both the protein and RNA levels of N-cadherin upon GH treatment, while GHR knockdown downregulates the N-cadherin expression in melanoma." (PMID 39123364, 2024). "Research from our laboratory and others has shown that inhibiting the GHR action sensitizes the human melanoma cells to chemotherapy by reducing the expression of ABC drug efflux pumps." (PMID 39123364, 2024). "Metastatic melanoma cell lines have also been shown to have an increased level of growth hormone receptor (GHR)." (PMID 36676131, 2023). "The GHR melanoma solid tumors displayed four major phenotypes using equipartition based on the expression levels of PD-1, and the remaining new subgroups were assigned to these four categories." (PMID 37433793, 2023). "Although GHR is expressed in virtually all cells of the body, especially melanoma, breast, lung, ovarian and prostate, cancers are high expressors." (PMID 35966052, 2022). "Despite significant heterogeneity in patient treatment types, the TCGA melanoma patient dataset confirms a positive correlation of GHR and ABC transporters." (PMID 35865483, 2022). "Several studies report elevated levels of RNA and GHR proteins in human melanoma biopsies, while the cell cycle of melanoma cells has been shown to be subject to orchestrated regulation of endogenous GH, prolactin (PRL) and adrenocorticotropic hormone (ACTH)." (PMID 35160191, 2022). "Recent reports have confirmed higher levels of growth hormone (GH) receptor (GHR) transcripts in malignant melanomas (MM), yet the role of GH in the pathogenesis of MM remains controversial." (PMID 35160191, 2022).